VCL (vinculin)
Diseases named in the same sentence as VCL in open-access papers (continued):
Sharing a sentence is not in itself a finding about the gene and the disease.
experimental autoimmune encephalomyelitis (1 paper, 2021). An autoimmune demyelinating disease of the central nervous system that is produced experimentally in animals by the injection of homogenized brain or spinal cord in Freund's adjuvant. "Downregulated vinculin affected BBB permeability by damaging the adhesion structure in the mice brain model of experimental autoimmune encephalomyelitis." (PMID 34068233, 2021).
follicular thyroid cancer (1 paper, 2020). "Similar findings were reported after 24- and 48-h clinostat-exposures of poorly differentiated follicular thyroid cancer cells exhibiting increased expression of vinculin and among other ECM proteins as well as fibronectin in MCS compared with 1 g controls." (PMID 32070055, 2020).
frontal encephalocele (1 paper, 2020). "In 5 cases of frontal encephalocele and occipital cervical spina bifida aperta, we observed 3 PDRVs in the cytoskeleton genes SHROOM2, SHROOM3, and VCL encoding VINCULLIN (P = 0.040)." (PMID 32650820, 2020).
fungal infections (1 paper, 2024). "Additionally, other studies have found that hyperferritinemia and elevated plasma levels of adhesion molecules such as soluble intercellular adhesion molecule-1 (sICAM-1), thrombospondin-1, and vinculin promote invasive fungal infections." (PMID 39176311, 2024).
glomerulosclerosis (1 paper, 2022). A hardening of the kidney glomerulus caused by scarring of the blood vessels. "In addition to vinculin enhancement in KI mice, we also identified the increased expression of ECM proteins (collagen I and fibulin 2) and the reduced expression of integrin β1, which were reported to be involved in the process of glomerulosclerosis and primary FSGS, respectively." (PMID 36173685, 2022).
Hirschsprung disease (1 paper, 2025). Hirschsprung disease (HSCR) is a congenital intestinal motility disorder that is characterized by signs of intestinal obstruction due to the presence of an aganglionic segment of variable extent in the terminal part of the colon. "This study examines the role of VCL in the development of the enteric nervous system (ENS) and its relationship to Hirschsprung disease (HSCR)." (PMID 41364504, 2025).
HIV-1 infection (1 paper, 2023). The type species of lentivirus and the etiologic agent of acquired immunodeficiency syndrome (AIDS). "On other hand, VCL is dispensable for integrin-mediated uptake of S. aureus, and due to its negative effect on paxillin phosphorylation, VCL blocks the early stages of HIV-1 infection." (PMID 37023213, 2023).
Hyperinsulinemia (1 paper, 2020). An increased concentration of insulin in the blood. "Additionally, to our knowledge, vinculin has not been reported as an underlying mechanism of hyperinsulinemia but is known to be a substrate of protein kinase C, which is part of the insulin signaling pathway." (PMID 32596266, 2020).
kidney damage (1 paper, 2025). "To investigate the pathogenicity of anti-vinculin autoantibodies in the kidneys, we administered anti-vinculin antibodies to mice via tail vein injection to mimic passive immunity and monitored the development of kidney damage." (PMID 40463498, 2025).
low grade glioma (1 paper, 2025). A grade I or grade II glioma arising from the central nervous system. "Other relevant pathways in cancer, such as focal adhesion, cytoskeleton regulation, and chemokine signalling (VCL, THBS1-4, FLNA, LAMA2/4/5, HSPG2), might also be influenced indirectly by changes in the WWOX/HIF1A ratio, potentially impacting the overall prognosis of low-grade glioma patients." (PMID 41007296, 2025).
malaria (1 paper, 2009). Malaria is a serious and sometimes fatal disease caused by a parasite that commonly infects a certain type of mosquito which feeds on humans. "Quantitative PCR of human umbilical vascular endothelial cells (HUVECs) cultured with P. falciparum samples from patients with uncomplicated malaria showed increased mRNA levels of occludin, vinculin, and ZO-1." (PMID 19680452, 2009).
metastatic cancer (1 paper, 2012). A carcinoma which has spread from the original site of growth to another anatomic site. "Thus, we evaluated the effect of caveolin-1 on FA turnover in metastatic cancer cells by transfection with GFP-vinculin followed by time-lapse videomicroscopy analysis." (PMID 22505999, 2012).
myofibrillar myopathy (1 paper, 2016). "Sequestration of Z-disc proteins to ectopic intracellular aggregates has been implicated in the muscle phenotypes associated with myofibrillar myopathy, and a similar effect may be stimulated by hyperactive vinculin." (PMID 27737911, 2016).
neuroblastoma (1 paper, 2025). Neuroblastoma (NB) is the most common solid, extracranial childhood tumor. "(D) A western blot analysis of FMR99xG normalized to Vinculin from the human neuroblastoma cell line (SH-SY5Y) upon silencing of either RPS26 or RPS25." (PMID 40377206, 2025).
neuroendocrine tumours (1 paper, 2009). "Low levels of vinculin have been found in highly malignant neuroendocrine tumours." (PMID 19367286, 2009). "Therefore vinculin is thought to play a role in growth regulation of neuroendocrine tumours." (PMID 19367286, 2009).
Osteopenia (1 paper, 2025). Osteopenia is a term to define bone density that is not normal but also not as low as osteoporosis. "Micro-computed tomography (μCT) analysis of distal femurs from 3- and 14-month-old male control and cKO mice showed that vinculin loss caused a severe osteopenia at both ages." (PMID 40796727, 2025).
osteoradionecrosis (1 paper, 2020). Necrosis of bone following radiation injury. "The mechanism may lie in the significant elevation of the expression of RhoA, ROCK, vinculin, and the ratio of p-FAK/FAK by regulating the RhoA/ROCK signaling pathway, thereby providing experimental evidence and modifying the target of LIPUS in osteoradionecrosis treatment practice." (PMID 32952571, 2020).
pancreatic adenocarcinoma (1 paper, 2020). "Moreover, VCL has been identified as a potential novel oncogene in pancreatic adenocarcinoma." (PMID 33362865, 2020).
periodontal disease (1 paper, 2023). "We revealed a role for VCL in modulating the macrophage inflammatory response and improving bactericidal activity, effects that should be protective in periodontal disease in vivo." (PMID 37023213, 2023).
peripheral artery diseases (1 paper, 2022). "The common SNP rs3812625 of VCL was also significantly associated with coronary and peripheral artery diseases in the PheWAS analysis." (PMID 36362053, 2022).
peritonitis (1 paper, 2020). Inflammation of the peritoneum (tissue that lines the abdominal wall and covers most of the organs in the abdomen). "Considering that vinculin expression is unnecessary for neutrophil recruitment using a murine model of acute peritonitis, it remains unclear whether this might be because rigidity sensing by neutrophils does not play a role in their recruitment to this specific tissue." (PMID 32034208, 2020). "Despite the in vitro defect observed in neutrophils lacking vinculin, there was no in vivo phenotype as assessed in a classical recruitment model of acute peritonitis." (PMID 32034208, 2020).
pneumonia (1 paper, 2014). An acute, acute and chronic, or chronic inflammation focally or diffusely affecting the lung parenchyma, caused by an infection in one or both of the lungs (by bacteria, viruses, fungi, or mycoplasma.). "Vinculin might be a target of therapy for various S. aureus-induced diseases including pneumonia." (PMID 24466349, 2014).
postmenopausal osteoporosis (1 paper, 2025). Metabolic disorder associated with fractures of the femoral neck, vertebrae, and distal forearm. "Vinculin expression in osteocytes was further determined in mice subjected to ovariectomy (OVX), a procedure that mimics postmenopausal osteoporosis in humans." (PMID 40796727, 2025).
pulmonary fibrosis (1 paper, 2022). Chronic progressive interstitial lung disorder characterized by the replacement of the lung tissue by connective tissue, leading to progressive dyspnea, respiratory failure, or right heart failure. "Hence, more research is needed to evaluate if anti-vinculin antibodies can be utilized to diagnose pulmonary fibrosis in SSc patients." (PMID 35876914, 2022). "Vinculin dysregulation may aggravate pulmonary fibrosis in SSc patients." (PMID 35876914, 2022).
renal fibrosis (1 paper, 2025). A final common manifestation of a wide variety of chronic kidney diseases characterized by glomerulosclerosis and tubulointerstitial fibrosis. "Dysregulation of vinculin’s biological function may be intricately associated with inflammatory responses, apoptosis, oxidative stress-induced injury, and renal fibrosis in DN." (PMID 39953202, 2025).
renal medullary carcinoma (1 paper, 2017). "Because the original RCCs with VCL-ALK fusion showed morphological features similar to those in renal medullary carcinoma, they were incorrectly classified as renal medullary carcinoma." (PMID 28850056, 2017).
Salmonella Infections (1 paper, 2013). Infections with bacteria of the genus SALMONELLA. "Accordingly, our RT-qPCR data showed decreased COL4A1 as well as VCL expression upon Salmonella infection." (PMID 23826261, 2013). "Our integrated analysis of miRNA and mRNA expression in intestinal Salmonella infection pointed out that FA members such as VCL and CAV2 but also ECM proteins that are involved in FA formation are controlled by miRNAs, particularly by miR-29a." (PMID 23826261, 2013).
schizophrenia (1 paper, 2022). A major psychotic disorder characterized by abnormalities in the perception or expression of reality. "Authors also reported an increased ratio of IgM towards components of the paracellular route (zonulin + occludin)/components of the transcellular route (talin + actin + vinculin) in deficit v. non-deficit schizophrenia and in schizophrenia v. controls." (PMID 35506416, 2022).
scleroderma (1 paper, 2022). Scleroderma is a rare autoimmune connective tissue disorder characterized by abnormal hardening of the skin and, sometimes, other organs. "Anti-vinculin antibodies in the blood appear to be diagnostic biomarkers for scleroderma." (PMID 35876914, 2022). "Further research with a larger sample size will be needed to verify whether anti-vinculin cutoff levels can be used for the diagnosis of scleroderma and to differentiate between PAH and ILD." (PMID 35876914, 2022). "In ILD-predominant scleroderma cases, anti-vinculin positivity was associated with a higher proportion of CT nodular opacity and honeycombing and a lower proportion of CT ground-glass opacity." (PMID 35876914, 2022). "Scleroderma patients’ susceptibility to IPF has not been studied using serum antibodies to the vinculin protein." (PMID 35876914, 2022). "In addition, anti-vinculin antibodies may provide new insights into the pathophysiology of some lung fibrotic changes, such as CT nodular opacity and honeycombing in ILD associated with scleroderma." (PMID 35876914, 2022). "Scleroderma patients’ vulnerability to IPF has not been studied using serum antibodies to the vinculin protein." (PMID 35876914, 2022). "Anti-vinculin antibodies may serve as biomarkers for scleroderma, allowing scleroderma to be an inclusion diagnosis rather than an exclusion diagnosis, and may aid in the targeting investigations in those who tested negative, given that not all scleroderma subjects test positive for this biomarker." (PMID 35876914, 2022).
seminoma (1 paper, 2021). A radiosensitive malignant germ cell tumor found in the testis (especially undescended), and extragonadal sites (anterior mediastinum and pineal gland). "Of them, 14-3-3γ, ezrin, filamin A, Parkinsonism-associated deglycase 7 (PARK7), vimentin and vinculin, were validated in CS I seminoma patient cohort." (PMID 34771736, 2021). "While 14-3-3γ, ezrin, filamin A, PARK7, vinculin and vimentin could be analysed in cohort of CS I seminoma patients using IHC to validate their clinical relevance, IHC evaluation in the case of caldesmon and 14-3-3β failed (data were non-homogenous and suboptimal)." (PMID 34771736, 2021).
spondyloarthritis (1 paper, 2025). "It is evident that the high expression of S100A8, S100A9, SERPING1, ZYZ, VCL, and FERMT3 is positively correlated with spondyloarthritis." (PMID 39877611, 2025).
Stroke (1 paper, 2023). Sudden impairment of blood flow to a part of the brain due to occlusion or rupture of an artery to the brain. "In summarizing this study, we affirm that our risk assessment model, based on PADGs, specifically APP, THBS1, F13A1, SRC, PPBP, and VCL, presents robust diagnostic capabilities for stroke patients." (PMID 38268925, 2023).
uremia (1 paper, 2018). A clinical syndrome associated with the retention of renal waste products or uremic toxins in the blood. "Second, the evaluation of the effect of uremia on VE-cadherin phosphorylation and its internalization, as well the extensive involvement of p120, β-catenin, vinculin proteins, besides elucidating the ZO-1 protein regulation mechanisms, should be deeply investigated." (PMID 30301260, 2018).
cancer (96 papers, 2008 to 2026). A tumor composed of atypical neoplastic, often pleomorphic cells that invade other tissues. "The reduction of vinculin expression in focal contacts has been associated with metastatic behavior of cancer cells." (PMID 39451527, 2024). "For this, we expressed GFP-tagged versions of vinculin Y822F, a mutant protein unable to be phosphorylated, and vinculin Y822C, a cancer mutation identified in The Cancer Genome Atlas (TCGA) database." (PMID 37248996, 2023). "The expression levels of integrins were concomitant with a decrease of and disruption in vinculin-associated focal adhesions, which can be signs of cancer and other diseases." (PMID 36647127, 2023). "SPL expression modulated the invadopodium-associated protein vinculin to regulate cancer cell migration." (PMID 33768098, 2021). "This reduced expression of vinculin in the presence of lumican in the highly metastatic Snail-B16F1 cells underlines the anti-cancer action of lumican." (PMID 33917849, 2021). "We tested the ability of αT-catenin to restore cell–cell adhesion and recruit vinculin in α-catenin-deficient R2/7 carcinoma cells." (PMID 33771561, 2021). "It will be interesting to determine whether the contrasting expression of VCL in tissues and exosomes reflects selective sorting related to metastatic progression or merely mirrors cancer progression-associated changes." (PMID 40563579, 2025). "A study shows that the VCL gene is significantly associated with cancer." (PMID 38435719, 2024). "In the existing literature, the loss of vinculin is linked to the development of many cancers." (PMID 36052248, 2022). "Vinculin associates with VE-cadherin on the EC junctions as a regulator force-dependent remodeling and deregulation of Vinculin is associated with enhanced cancer cell migration." (PMID 32595503, 2020). "C12-HSL treatment induced cytoskeletal associated protein expression of vinculin and RhoC, which may have implications in cancer cell motility, adhesion, and metastasis." (PMID 29854771, 2018). "Importantly, genes associated with cancer progression (i.e., Itgb2, Itgb5, paxillin, fyn) displayed increased expression, whereas those thought to suppress progression (i.e., vinculin, gravin) exhibited decreased levels of expression compared to MOSE-E cells." (PMID 21390237, 2011). "Thus, the Y822F-expressing cells are more spread, have larger focal adhesions, and are more contractile than cells expressing Y822C or wild-type vinculin, thereby suggesting that the two Y822 mutations differentially affect focal adhesion biology in cancer cells." (PMID 37248996, 2023). "In this study, cancer cells were found to associate directly with fibroblasts by establishing E- and N-cadherin heterotypic interactions, which attained adhesive resistance and mechanical strength, allowing the collective invasion of cancer cells through their associations with α-catenin/vinculin." (PMID 28721207, 2017). "Labernadie and colleagues discovered a mechanism wherein CAFs apply physical force to cancer cells via heterophilic adhesion involving N-cadherin on CAFs and E-cadherin on cancer cells, mediated by β-catenin and α-catenin/vinculin interactions." (PMID 40313969, 2025). "The coding can occur at the level of single proteins, such as the focal adhesion proteins talin and vinculin or at the level of multicellular assemblies, such as a collection of cancer cells." (PMID 41227352, 2025). "Malate dehydrogenase, hepatoma‐derived growth factor, Vinculin, Zinc finger protein 521, and neural cell adhesion molecule L1 contribute to cancer cell proliferation and growth." (PMID 39801758, 2025). "Pathway analysis revealed that miR-206-3p is involved in critical cancer-related pathways, while VCL exhibited distinctive expression patterns between tissues and exosomes during metastasis progression." (PMID 40563579, 2025).